RHD (Rh blood group D antigen)
Diseases named in the same sentence as RHD in open-access papers (continued):
Sharing a sentence is not in itself a finding about the gene and the disease.
sickle cell disease (2 papers, 2017 to 2022). Sickle cell anemias are chronic hemolytic diseases that may induce three types of acute accidents: severe anemia, severe bacterial infections, and ischemic vasoocclusive accidents (VOA) caused by sickle-shaped red blood cells obstructing small blood vessels and capillaries. "Similarly, despite an allele frequency of 1–2% in black donors, in African and in SCD (sickle cell disease) patients, this allele was not reported in studies of RHD variants in patients with weak/inconsistent RhD antigen." (PMID 35741820, 2022).
syphilis (2 papers, 2009 to 2020). A contagious bacterial infection caused by the spirochete Treponema pallidum. "ABO and RhD typing and screening for HIV and syphilis were undertaken in all transfused blood." (PMID 19682362, 2009).
amenorrhea (1 paper, 2021). The absence of menses in a woman who has achieved reproductive age. "RhD-cffDNA in maternal plasma were detected between weeks 14 and 24 of amenorrhea using free DNA Fetal RHD Kit® (Biorad®)." (PMID 33407582, 2021).
Anxiety (1 paper, 2023). Intense feelings of nervousness, tension, or panic often arise in response to interpersonal stresses. "NIPT for fetal antigen can decrease patient risk and anxiety, as well as healthcare burden, namely by reducing the administration of Rho(D) immune globulin, which is unnecessary for the up to 40% of RhD-negative pregnant individuals carrying an RhD-negative fetus." (PMID 37550335, 2023). "Clinical adoption of NIPT for the detection of fetal antigens for both alloimmunized and RhD-negative non-alloimmunized pregnant individuals may streamline care and reduce unnecessary treatment, monitoring, and patient anxiety." (PMID 37550335, 2023).
Autoimmunity (1 paper, 2015). The occurrence of an immune reaction against the organism's own cells or tissues. "The general pattern suggests that RhD negative subjects could have problems with autoimmunity, could be more resistant to infections of viral origin and could be less resistant to infections of bacterial origin." (PMID 26495842, 2015).
congenital adrenal hyperplasia (1 paper, 2013). Congenital adrenal hyperplasia (CAH) is an inherited endocrine disorder caused by a steroidogenic enzyme deficiency that is characterized by adrenal insufficiency and variable degrees of hyper or hypo androgyny manifestations, depending of the type and the severity of the disease. "Early clinical applications of fetal cfDNA for prenatal testing included fetal RhD genotyping and sex determination to aid in the risk assessment of X-linked disorders and congenital adrenal hyperplasia (CAH) utilizing the detection of Y-chromosomes in the plasma of women pregnant with male fetuses." (PMID 23687624, 2013).
Dyskinesia (1 paper, 2021). A movement disorder which consists of effects including diminished voluntary movements and the presence of involuntary movements. "ADAM32 (Hoehn and Yahr), IRAK3 (dyskinesia), LMAN1 (UPDRS part 2), and RHD (dyskinesia) passed MR-Egger intercept, Cochran’s Q and I2 tests." (PMID 34930919, 2021). "Our evidence suggests that RHD expression in brain tissue, rather than blood, is associated with PD dyskinesia." (PMID 34930919, 2021).
dyslipidaemia (1 paper, 2025). "In this study, we sought to investigate whether the ABO blood groups and RhD factor are associated with dyslipidaemia." (PMID 39844181, 2025). "Thus, the RhD blood group, but not ABO, seems to be associated with dyslipidaemia and may act as a future possible risk marker of cardiovascular disease." (PMID 39844181, 2025).
fetomaternal hemorrhage (1 paper, 2014). "This study aimed to assess fetomaternal hemorrhage (FMH) among RhD negative pregnant mothers using two techniques, Kleihauer-Betke (KBT) and Flow cytometry (FCM)." (PMID 25381160, 2014).
myelodysplastic syndrome (1 paper, 2025). A clonal hematopoietic disorder characterized by dysplasia and ineffective hematopoiesis in one or more of the hematopoietic cell lines. "An 83-year-old Thai female patient with a blood group of A RhD-positive had been diagnosed with myelodysplastic syndrome (MDS) in 2017." (PMID 40242488, 2025). "In this report, we describe the identification of anti-IH in a patient with myelodysplastic syndrome (MDS) and A RhD-positive blood group during pre-transfusion testing." (PMID 40242488, 2025).
osteosarcoma (1 paper, 2023). A usually aggressive malignant bone-forming mesenchymal neoplasm, predominantly affecting adolescents and young adults. "HSPB8/RHD/AASS/NFASC has not yet been found to be associated with osteosarcoma." (PMID 36983630, 2023). "HSPB8, RHD, AASS, and NFASC were genes we identified that have not been previously reported to be associated with osteosarcoma." (PMID 36983630, 2023).
placenta previa (1 paper, 2025). "The patient received RhIG at 21 weeks for bleeding (placenta previa), 28 weeks, and postpartum after delivering an RhD‐positive newborn (not genotyped) at 37 weeks." (PMID 40999654, 2025).
primary hypertension (1 paper, 2024). "However, this is also contradictory to the few available studies including the RhD blood group, since they found that RhD+ individuals have an increased risk for primary hypertension." (PMID 38592146, 2024).
rheumatoid arthritis (1 paper, 2015). A chronic, systemic autoimmune disorder characterized by inflammation in the synovial membranes and articular surfaces. "RhD negative subjects have increased the risk of developing of certain heart diseases, respiratory diseases and some immunity and autoimmunity related diseases, for example rheumatoid arthritis." (PMID 26495842, 2015).
Thrombocytopenia (1 paper, 2020). A reduction in the number of circulating thrombocytes. "Since we noticed that the prevalence of thrombocytopenia was significantly much lower in RhD-positive phenotype patients than RhD-negative ones, the Rh factor might also play a protective role." (PMID 32595711, 2020). "The prevalence of thrombocytopenia was significantly much lower in RhD-positive phenotype patients than RhD-negative ones (13.6% vs. 71.4%, P=0.008, OR=0.1, CI= 0.01 to 0.48)." (PMID 32595711, 2020).
infection (13 papers, 2009 to 2025). The state of being infected such as from the introduction of a foreign agent such as serum, vaccine, antigenic substance or organism. "RhD status also appears to affect susceptibility to SARS-CoV-2; in a study of 14,112 donors, RhD-negative individuals had a lower risk of initial infection, intubation and death- suggesting a protective role for RhD negativity." (PMID 35428875, 2022). "Research on the behavioral and health effects of chronic Toxoplasma infection led to the discovery that RhD heterozygosity may confer protection against certain adverse outcomes associated with infection." (PMID 40722801, 2025). "Conceivably, being RhD negative could confer some level of protection against HIV infection, or conversely the presence of RhD antigen in the host cell may act as viral receptor sites for HIV and increase the risk of infection in RhD positive individuals." (PMID 37099490, 2023). "This method allowed us to detect simultaneously the RhD surface expression on RBCs and their infection status, through P. vivax 18 S rRNA expression." (PMID 35840625, 2022). "This conclusion was supported by the FlowFISH experiment, where Pvs25+ 18S+ gametocytes were detected within RhD+ CD235a+ BM RBCs on day 7 post-infection (lower row)." (PMID 35840625, 2022). "The highest percentage of HBcAb infection (1.8859%) was found among the donors who had the O RhD +ve blood group, while the lowest (0.0122%) was among donors who had the AB RhD −ve blood group." (PMID 35888577, 2022). "The percentages of TTIs infection were found to be higher in RhD + ve donors compared with RhD − ve donors." (PMID 33339085, 2020). "RhD-negative individuals have reduced risk of initial infection with SARS-CoV-2, as well as decreased risk of both intubation and death." (PMID 35428875, 2022). "Our population of RhD-positive drivers includes both RhD-positive heterozygotes and RhD-positive homozygotes (some of them with relatively low concentration of anti-Toxoplasma antibodies and therefore relatively old infection)." (PMID 19470165, 2009). "The increased IFNγ signalling found here in RhD-negative males may begin to explain their reduced susceptibility to infection." (PMID 35428875, 2022). "RhD-negative individuals also appear to be protected against certain infections, including latent toxoplasmosis." (PMID 35428875, 2022). "And in this study, all individuals in the case group and in the control group were RhD positive, so we cannot make any conclusion about whether RhD status could affect HFRS infection, which is inherent to the studied populations." (PMID 34583784, 2021). "The enhanced signature observed in RhD-negative individuals in our cohort may contribute to the increased resistance to infection described in these individuals." (PMID 35428875, 2022). "The psychomotor performance of RhD-negative homozygotes decreases immediately after infection." (PMID 19470165, 2009).
cancer (4 papers, 2015 to 2023). A tumor composed of atypical neoplastic, often pleomorphic cells that invade other tissues. "We found the ABO/RhD blood groups to be associated with a wide spectrum of diseases including cancers and musculoskeletal-, genitourinary-, endocrinal-, infectious-, cardiovascular-, and gastrointestinal diseases." (PMID 36892462, 2023).
infectious disease (3 papers, 2015 to 2022). A disorder directly resulting from the presence and activity of a microbial, viral, or parasitic agent in humans. "Reports suggest that RhD-negative individuals are better protected against infectious diseases and have overall better health." (PMID 35428875, 2022). "In contrast, RhD-positive homozygote men reported better physical condition at the time of blood sample-taking, a higher life expectancy, and less frequent common infectious diseases than RhD-negative homozygote men." (PMID 34753960, 2021). "For example, a partial Kendall’s Tau -0.429 for common infectious diseases was equivalent to R2 0.49, which means that RHD genotype was responsible for nearly 50% of the variability in the frequencies of common infectious diseases in the sample of male RhD-positive and negative homozygotes." (PMID 34753960, 2021).
bacterial diseases (2 papers, 2012 to 2025). "Ordinal probit regression revealed nearly significant effect of age (p = 0.058) and signifiant effect of smoking-RhD interaction (p = 0.040) on health (number of viral and bacterial diseases in the past year)." (PMID 23209579, 2012). "Already discussed cross-sectional study performed on 3800 draftees showed the adverse effect of smoking on the number of viral and bacterial diseases was about three times stronger for RhD-negative than RhD-positive subjects." (PMID 40722801, 2025). "Our data showed that the negative effect of smoking on health (estimated on the basis of the self-rated number of common viral and bacterial diseases in the past year) was much stronger in RhD-negative than RhD-positive subjects." (PMID 23209579, 2012). "The negative effect of smoking on health (estimated on the basis of the self-rated number of common viral and bacterial diseases in the past year) was much stronger in RhD-negative than RhD-positive subjects." (PMID 23209579, 2012).
cardiovascular disease (2 papers, 2016 to 2025). "For example, the protective effect of RhD negativity against many neuropsychiatric disorders observed in the present ecological study could be caused by the fact that RhD negative subjects usually die at an earlier age due to their higher susceptibility to cardiovascular diseases." (PMID 26811928, 2016).
tonsil (2 papers, 2015 to 2023). "The RhD-positive group was associated with a later diagnosis of acute and chronic tonsilitis diagnosis." (PMID 36892462, 2023).
blood disorder (1 paper, 2015). "In pregnancy, where the woman is RhD negative and the fetus is RhD positive, if fetal maternal haemorrhage occurs where fetal cells cross the placenta, it may stimulate antibody production which can cause Rh HDFN, a potentially fatal blood disorder." (PMID 26097401, 2015).
musculoskeletal diseases (1 paper, 2023). "In conclusion, we found the ABO/RhD blood groups to be associated with a wide spectrum of diseases, including cardiovascular-, infectious-, gastrointestinal- and musculoskeletal diseases." (PMID 36892462, 2023).
RHD also shares sentences with these, for which no sentence is quoted: tumor (24 papers); rhabdomyosarcoma (7); allergies (2); autoimmune hemolytic anemia (2); panic disorder (2); schizophrenia (2); scoliosis (2); thyroiditis (2); acute diarrhea diseases (1); allergic rhinitis (1); asthma (1); autoimmune disease (1); autoimmune pancreatitis (1); breast carcinoma (1); cholangiocarcinoma (1); chorioangioma (1); coeliac disease (1); depression (1); diabetes (1); Down syndrome (1); Edwards Syndrome (1); embryonal rhabdomyosarcoma (1); erythroleukemia (1); Ewing sarcoma (1); gastrointestinal disease (1); glaucoma (1); Headache (1); healthcare-associated infections (1); heart diseases (1); Hemolytic Disease of the Fetus and Newborn (1).
A further 35 diseases each share a sentence with RHD in 1 paper.